INS (insulin)
Diseases named in the same sentence as INS in open-access papers (continued):
Sharing a sentence is not in itself a finding about the gene and the disease.
Hyperinsulinemia (continued). "Since there is an opposite association between SHBG serum levels and insulin, the presence of hyperinsulinemia in these people can inhibit hepatic synthesis of SHBG." (PMID 24639805, 2013). "As IR is associated with compensatory increased insulin secretion, hyperinsulinemia associated with PCOS is usually considered a consequence of IR." (PMID 23457541, 2013). "Association of lower HDL-cholesterol with higher daily insulin dose is consistent and it points out to a role of exogenous hyperinsulinemia in the pathophysiology of the CVRF clustering." (PMID 23270560, 2012). "In summary, this report confirms the association of the major C-allele of rs2943641 near IRS1 with increased risk of T2D, fasting- and glucose-stimulated hyperinsulinemia and impaired insulin sensitivity." (PMID 21917432, 2012). "In insulin resistant animals, hyperinsulinemia is associated with the elevated hepatic gluconeogenesis and lipogenesis, which should have been respectively suppressed and stimulated by insulin." (PMID 23028851, 2012). "Hyperinsulinemia is associated with hepatic steatosis and hyperlipidemia in humans and animal models, and treatment with insulin-sensitizing drugs ameliorates these conditions." (PMID 21211044, 2011). "An additional infusion of somatostatin into hyperinsulinemic fetuses blocked fetal hyperinsulinemia and completely prevented these increases, specifying insulin as a causative factor." (PMID 21668983, 2011). "Insulin clearance is decreased in advanced liver disease, which is regarded as one of the main causes of hyperinsulinemia in iver cirrhosis." (PMID 20426802, 2010). "Although increased plasma insulin levels should be associated with reduction in appetite, the hyperinsulinemia seen in CR animals, associated with hyperphagia, is likely to reflect reduced central insulin action." (PMID 20796266, 2010). "An exception to this notion is that HNF4A mutations cause transient in utero and neonatal hyperinsulinism, which later evolves to decreased insulin secretion, whereas HNF1A mutations develop the latter phenotype without early hyperinsulinism." (PMID 20523905, 2010). "Unfortunately, several epidemiological studies have shown that a high level of circulating insulin (hyperinsulinemia) is associated with an increased risk for a number of malignancies." (PMID 19609453, 2009). "ALK7 deficient mice have hyperinsulinemia, reduced insulin sensitivity and impaired glucose tolerance." (PMID 19275893, 2009). "Under insulin resistant condition, loss of this response triggers an elevation of circulating insulin, resulting into hyperinsulinemia." (PMID 18771597, 2008). "Because of this fact, in patients with insulinoma, a condition characterized by marked hyperinsulinemia, downregulation of insulin receptors induced by elevated plasma insulin was associated with increased abundance of hybrid insulin/IGF-I receptors." (PMID 19902049, 2008). "In our earlier studies, hair loss in 63-year-old women was suggested to be associated with insulin-linked disturbances, such as overweight, hyperinsulinemia and microalbuminuria." (PMID 16120206, 2005). "Although a state of endogenous hyperinsulinemia occurs, the degree of tissue resistance causes a total decrease in “effective” endogenous insulin." (PMID 15736996, 2005). "Sepsis often induces metabolic dysregulation and IR, which engage in a bidirectional pathogenic cycle: systemic inflammation impairs insulin signaling, leading to IR, while IR-associated hyperinsulinemia promotes immunometabolic reprogramming and exacerbates inflammation." (PMID 41601726, 2026). "Indeed, vigorous exercise prevents the reduction of insulin sensitivity, development of hyperinsulinemia, and altered expression of numerous genes caused by reduced physical activity and short-term overfeeding, which ultimately regulate DNL." (PMID 40004991, 2025).
Hyperinsulinemia (continued). "The administration of BSA to mice reduced the hyperinsulinemia caused by the PC diet, which conceivably increased the insulin sensitivity of the adipose tissue, normalising lipolysis and thus reducing circulating NEFA, translating to reduced triglyceride accumulation in the liver." (PMID 40806286, 2025). "Therefore, tissues require higher concentrations of insulin to achieve a physiological response, leading to compensatory hyperinsulinemia, which is the typical diagnostic hallmark of IR." (PMID 40235665, 2025). "Besides leading to gluconeogenesis and causing more insulin to be secreted, hyperinsulinemia is reinforced by lower rates of insulin clearing in MASLD." (PMID 39826021, 2025). "Similarly, aging in rhesus is associated with hyperinsulinemia, reduced glucose clearance, elevated fasting glucose, and diminished insulin secretion." (PMID 40927358, 2025). "Second, compensatory hyperinsulinemia is a hallmark of DM that may be further exacerbated by exogenous insulin." (PMID 41464751, 2025). "Chronic elevation of insulin (hyperinsulinemia) may be a precursor to insulin receptor sensitivity loss and metabolic disease." (PMID 41277758, 2025). "This may cause compensatory insulin secretion to sustain glucose homeostasis, which leads to hyperinsulinemia." (PMID 40008316, 2025). "Concerning the underlying mechanisms, multiple lines of evidence have demonstrated that a strong positive association exists between hyperinsulinemia and hyperuricemia, indicating that insulin signaling may play a pathogenic role." (PMID 40100301, 2025). "This phenomenon of reduced cells’ response to insulin leads to hyperinsulinemia, which occurs due to genetic polymorphisms; tyrosine phosphorylation of the insulin receptor, insulin receptor proteins, PIP-3 kinase; or abnormalities of GLUT 4 function; and/or environmental factors." (PMID 40943177, 2025). "Our results concur with prior research showing that hyperinsulinemia is a modifiable risk factor for metabolic deterioration, even in people with normoglycemia, and that small changes in insulin levels can affect lipid accumulation and adipogenesis independent of glucose homeostasis." (PMID 40502600, 2025). "Increased BC risk related to hyperinsulinemia could be attributed to a synergistic interaction between elevated free estrogen concentrations and aberrant INS signaling." (PMID 41221514, 2025). "Thus, insulin levels are normal but fail to activate the signal for glucose uptake, forcing the body to overstimulate pancreatic β cells, causing hyperinsulinemia to maintain optimal blood glucose levels." (PMID 40362446, 2025). "In T2DM, peripheral hyperinsulinemia causes increased levels of insulin." (PMID 39859258, 2025). "This altered insulin dynamic may contribute to variations in insulin sensitivity and β-cell stress, potentially predisposing certain individuals to compensatory hyperinsulinemia." (PMID 40806495, 2025). "Additionally, the urate transporter GLUT9 in the kidney is stimulated by insulin and can modulate the association between hyperinsulinemia and hyperuricemia." (PMID 40100301, 2025). "Similarly, plant-based diets rich in fiber improve insulin sensitivity and reduce hyperinsulinemia, further mitigating cancer risk." (PMID 40428567, 2025). "Thus, in this animal model, modest hyperinsulinemia was sufficient to cause adipose tissue inflammation and to suppress insulin-stimulated de novo lipogenesis in fat cells." (PMID 41009753, 2025). "Since insulin acts as a co-gonadotrophin at the ovary, iatrogenic hyperinsulinism might trigger androgen secretion in predisposed women." (PMID 40747135, 2025). "Of the pro-hypertensive mechanisms that may be associated with hyperinsulinemia, those related to the renal antidiuretic effect of insulin appear to be the most relevant." (PMID 38841306, 2024).
Hyperinsulinemia (continued). "This paradox may be explained by the increased insulin resistance and the compensatory intra-portal hyperinsulinemia causing increased hepatic GH sensitivity that increases serum IGF-I and blunts pituitary GH secretion via the negative feedback loop." (PMID 39665021, 2024). "If hyperinsulinemia is the key link between increased cancer risk and T2D, individuals with T1D, who receive less exogenously administered insulin, might exhibit a different cancer risk pattern." (PMID 38534454, 2024). "Hyperinsulinemia is caused by chronic elevated levels of insulin in serum." (PMID 38392069, 2024). "During pediatric age, hyperinsulinemia can have a genetic basis, being caused by molecular alterations in insulin secretion or in insulin receptor response; these alterations can be classified as isolated hyperinsulinemia or as part of the clinical presentation of various genetic syndromes." (PMID 38920551, 2024). "The WD may play a causal role in the development of hyperinsulinemia and IR prior to weight gain, as they lead to elevated levels of both insulin and OS." (PMID 38892561, 2024). "Therefore, the observed basal hyperinsulinemia was likely the result of compensatory pancreatic insulin secretion and/or reduced hepatic insulin clearance associated with IR." (PMID 39682351, 2024). "The decreased glucose tolerance on HFD causes increasing demands on insulin synthesis to try to maintain normoglycemia and with the associated insulin resistance in tissues, pancreatic β- cells respond by producing more insulin, a vicious cycle leading to hyperinsulinemia." (PMID 39150520, 2024). "Recent observations in humans have shown that inhaled insulin can cause an abrupt loss in lung function due to airway smooth muscle contraction, suggesting that hyperinsulinemia may increase airway smooth muscle bulk or contraction." (PMID 38398039, 2024). "Insulin plays a crucial role in neuronal survival, protein synthesis, and synaptic metabolism, and chronic hyperinsulinemia can cause insulin receptors in the blood-brain barrier to become deregulated, leading to brain insulin resistance and neural aging and degeneration." (PMID 39081608, 2024). "Additionally, insulin functions as a myocardial growth factor, and hyperinsulinemia has been shown in animal studies to cause myocardial hypertrophy, reduce cardiac output, and increase sodium retention." (PMID 39407941, 2024). "Since hyperinsulinemia is a key driver of tumor growth, agents like gliclazide that limit sustained insulin exposure may carry a lower oncogenic risk than those that promote persistent hyperinsulinemia." (PMID 39595655, 2024). "Higher insulin levels in the prediabetes group than in the T2D group at the remaining time points of OGTT seem to illustrate the pathogenesis of T2D, which involves a transition from hyperinsulinemia caused by IR to relative and then absolute deficit of insulin." (PMID 39125447, 2024). "Notably, in vitro evidence has shown that insulin resistance and hyperinsulinemia contribute to a high risk of PCa by altering the biological function of IGF-1 or IGF-2." (PMID 38243202, 2024). "Hyperinsulinemia, which may occur in the context of insulin therapy, has been associated with increased LC development." (PMID 39001440, 2024). "Reduced accumulation of ROS and enhanced bioenergetics could also explain why CR beta cells secrete less insulin, as dysregulation of ROS and glycolytic signaling are proposed as causes of basal hyperinsulinemia during diabetes." (PMID 39433757, 2024). "The effect of intranasal insulin might contradict expected outcomes given the associations between hyperinsulinemia and Aβ and tau described earlier." (PMID 38540695, 2024). "Conversely, insulin administered via subcutaneous injection first enters the peripheral systemic circulation and then enters the liver, which can easily cause peripheral hyperinsulinemia." (PMID 39000136, 2024).
Hyperinsulinemia (continued). "Moreover, hyperinsulinemia alone has been shown to increase AD risk, and the impacts of insulin on AD pathology seem to occur before clinical symptom onset." (PMID 38540695, 2024). "In line with this hypothesis, hyperinsulinemia is associated with more rapid tumor development in both mice and humans, whereas reducing insulin levels yields the opposite effect." (PMID 38510653, 2024). "However, in insulin-resistant states, often associated with hyperinsulinemia, this pathway is amplified, leading to the accumulation of large amounts of free fatty acids in the liver and facilitating NAFLD progression." (PMID 38732634, 2024). "There is interest in the physiological effects of dopamine on the endocrine pancreas due to evidence in people that dopamine receptor antagonists can cause hyperinsulinemia and glucose intolerance, while conversely, dopamine agonists can reduce insulin secretion and improve glycemic control." (PMID 38412155, 2024). "In addition, chronic sleep deprivation in those with migraine can cause hyperinsulinism due to higher postprandial glucose levels with abnormal insulin sensitivity." (PMID 39247924, 2024). "In the area of the pancreas in which only the paternal FHI gene is represented, insulin is overproduced and may cause hyperinsulinism of variable severity." (PMID 38791571, 2024). "And if it is suspected, generally it is considered to have more common causes outside of insulin, like drug side effects (sulfonylureas, antibiotics), alcohol, malnutrition, liver or kidney failure, and endocrine causes (endogenous hyperinsulinism and adrenal insufficiency)." (PMID 39138498, 2024). "Notably, aging in mice is associated with a declined capacity for insulin clearance resulting in hyperinsulinemia." (PMID 36992811, 2023). "The causal relationships between hyperinsulinemia and cancer are complicated and vary on a case-by-case basis but are believed to be caused by excessive stimulation of cell proliferation and growth by insulin and IR." (PMID 37779149, 2023). "Even though the precise relationship between Cdc42, insulin, and leptin in blood vessels is unknown, it is reasonable to assume that Cdc42 activation is linked to vascular remodeling caused by age-related hyperinsulinemia and hyperleptinemia." (PMID 38068822, 2023). "Hence, we developed an IR model using exogenous insulin administration to follow the stages of hyperinsulinemia, loss of insulin sensibility, and early IR." (PMID 37110230, 2023). "In addition, hyperinsulinemia or chronic insulin stimulation occurs in obese individuals is associated with tumor progression in TNBC by altering mitochondrial activity, histone modification, and several oncogenic signaling pathways." (PMID 36681663, 2023). "Indeed, ZnT8 deficiency prevents the hyperinsulinemia often observed with high fat intake and maintains insulin sensitivity." (PMID 38260166, 2023). "Moreover, hyperinsulinemia is another mechanism that causes endometrial cancer: the binding of insulin to insulin-receptors can stimulate the growth of endometrial stromal cells." (PMID 37480027, 2023). "A rise of maternal blood glucose causes hyperinsulinemia in the fetus, Insulin cannot be transported through the placenta, which promotes the deposition of liver glycogen, protein synthesis, and fat deposition in the fetus, thereby promoting growth and development." (PMID 37076792, 2023). "Our laboratory has shown that in mice, a mild exercise regime during an obese glucose-intolerant pregnancy results in a rescue of maternal hyperinsulinemia that is associated with a restoration of insulin sensitivity in offspring, and a prevention of cardiac hypertrophy in offspring." (PMID 37482780, 2023). "We discuss how basic mechanisms of cross-talk between insulin and insulin-growth factor 1 receptors could be linked to hyperinsulinemia and its associated comorbidities." (PMID 37885901, 2023).
Hyperinsulinemia (continued). "In addition, hyperinsulinemia was shown to be associated with impeded glucose metabolism and insulin signaling in several brain regions (e.g., frontal lobes, hippocampus) involved in planning and organizing." (PMID 37891743, 2023). "Hyperinsulinemia also promotes cancer, but the direct action of insulin on mutated endometrial epithelial cells is unknown." (PMID 37170094, 2023). "This hyperinsulinemia, associated with the inhibition of the glucose-6-phosphatase activity in the liver tissue, may suggest an insulin release caused by CGA." (PMID 36829899, 2023). "The mediation analyses showed that a higher insulin concentration which could reflect hyperinsulinemia was associated with higher total body fat mass." (PMID 38086810, 2023). "Decreased insulin sensitivity in hepatocytes as in other metabolic target tissues for this hormone causes compensatory hyperinsulinemia and up-regulation of lipogenic genes in the liver, leading to increased intracellular deposit of free fatty acids and triglycerides." (PMID 37111106, 2023). "It is therefore plausible that GEnC fenestration loss may result in decreased filtration of insulin contributing to hyperinsulinemia and decreased insulin receptor signaling in the kidney, resulting in decreased renal functioning and metabolism." (PMID 37471420, 2023). "In physiological conditions, insulin exerts a protective effect on the cardiovascular system by stimulating nitric oxide(NO) production; In pathological conditions, hyperinsulinemia may cause vascular damage." (PMID 38523869, 2023). "However, there are only a few epidemiological studies assessing the association between hyperglycaemia, hyperinsulinemia, or insulin-related traits and colorectal cancer, and the results remain inconclusive in Asians8–12." (PMID 37120602, 2023). "Furthermore, hyperinsulinemia has been found to cause activation of inflammatory signaling pathways in humans and rats, which can impair insulin sensitivity in the target tissues." (PMID 36902173, 2023). "Prospective studies are required to investigate whether an increase in insulin clearance, and consequently a reduction in hyperinsulinemia, does confer reduced risk from T2D in black Africans." (PMID 35831028, 2022). "Despite the strong epidemiological link between hyperinsulinemia and pancreatic cancer, the specific reduction of insulin is required to formally test the hypothesis that insulin plays a causal role." (PMID 35189981, 2022). "In this respect, it has been reported that hyperinsulinemia provokes the accumulation of iron into pancreatic β cells, which triggers the formation of radical oxygen species, causes mitochondrial dysfunction, and subsequently impairs insulin secretion." (PMID 36552647, 2022). "Much scientific interest is focused on improving insulin delivery technologies based on well-designed polymers to avoid adverse effects associated with the subcutaneous route of insulin administration, i.e., pain, lipodystrophy, and hyperinsulinemia." (PMID 36672580, 2022). "Persistent hyperinsulinemia is regarded as a causative factor and there is evidence that restoring the hepatic to peripheral gradient for insulin exposure and insulin action may mitigate risk of excessive weight gain." (PMID 35177603, 2022). "By this concept, reduced first-pass hepatic degradation of insulin—whether caused by genetic or environmental factors—results in peripheral hyperinsulinemia." (PMID 35163746, 2022). "By contrast, the substitution of animal proteins with plant proteins from high-GI, low-fiber foods was associated with a higher cancer risk at all the other colon subsites, possibly through insulin resistance and the compensatory hyperinsulinemia-mediated stimulation of the PI3K/AKT/AMPK pathway." (PMID 35740583, 2022).